IFI16 (interferon gamma inducible protein 16)
Diseases named in the same sentence as IFI16 in open-access papers (continued):
Sharing a sentence is not in itself a finding about the gene and the disease.
infection (115 papers, 2011 to 2026). The state of being infected such as from the introduction of a foreign agent such as serum, vaccine, antigenic substance or organism. "The PYHIN (pyrin and HIN domain-containing) gene family encodes central cytosolic DNA sensors, including AIM2 and IFI16, that activate inflammasome and type I interferon pathways during infection." (PMID 42292384, 2026). "Upon detection of RFP-tagged viral capsids at the outer nuclear periphery, we observed the simultaneous and adjacent association of WT, 6A or 6D IFI16-GFP puncta at the inner nuclear periphery during early infection with ICP0-RF HSV-1 at 2 hpi." (PMID 37283074, 2023). "PRR sensing by IFI16 during HSV-1 ΔICP0 infection correlates with IFI16 forming nuclear filaments on vDNA in association with PML following the saturation of PML-NBs under high genome loads." (PMID 32416261, 2020). "ATRX, PML, and IFI16 are associated with the HSV-1 genome within the first hour after infection, and initial heterochromatin formation is dependent on ATRX." (PMID 31500286, 2019). "Upon infection with herpesviruses, the IFI16 association with viral DNA is dynamic and temporally regulated." (PMID 31337724, 2019). "As a consequence of oligomerization, IFI16 can form filamentous structures in viral replication compartments after infection with an ICP0-deficient HSV-1, and it is thought that these structures restrict viral gene expression." (PMID 31500286, 2019). "There are several implications of the finding that the level of expression of NLRP3, NLRP12, and IFI16 inflammasomes is increase following infection virulent HSV-1 strains and this was associated with severe corneal inflammatory herpetic disease." (PMID 31367214, 2019). "As a DNA sensor, IFI16 stimulates the formation of inflammasomes in certain cell types during infection with Kaposi Sarcoma-associated herpesvirus, Herpes simplex virus 1, Epstein-Barr virus and Human immunodeficiency virus (HIV-1)." (PMID 27280708, 2016). "In addition, IFI16 is responsible for SUV39H1 recruitment to viral DNA during de novo infection and latency of Kaposi’s sarcoma-associated herpesvirus." (PMID 35350437, 2022). "For example, IFI16 detects viral DNA and initiates the assembly of inflammasome in both the cytoplasm and nucleus upon infection with DNA viruses such as Kaposi's sarcoma-associated herpesvirus (KSHV), Epstein-Barr virus (EBV) or herpes simplex virus (HSV-1) 25-28." (PMID 33061806, 2020). "Here, IFI16 was found to associate with the viral genome by 2 h post-infection." (PMID 33255247, 2020). "Latent infection of monocytes is associated with the downregulation of IFI16, MNDA, and HLA-DR." (PMID 31796538, 2019). "We next determined whether IFI16 associated H2B is also acetylated during infection to aid in cytoplasmic translocation." (PMID 27764250, 2016). "PYHIN1 and IFI16 have recently emerged as sensors of microbial DNA, and the innate immune response relies on the ability of immune cells to detect the presence of infection through these germline-encoded pattern recognition receptors." (PMID 24324648, 2013). "Furthermore, CCL2 expression driven by IFI16 recognition of HSV has been described to facilitate the recruitment of inflammatory monocytes to the infection site, as silencing of p204/IFI-16 resulted in the loss of CCL2 production and significantly more HSV shedding." (PMID 25918478, 2015). "Our ability to still detect some levels of IFI16 upon WT HSV-1 infection is due to our focus on an early time point of infection." (PMID 39772686, 2025). "RBM14 K600 and IFI16 K90 lactylation both promote virus spread by subverting host immunity, a feature that is shared during infection with HSV-1." (PMID 39772686, 2025). "The oncoprotein E7 of Human papillomavirus (HPV) recruits both TRIM21 and interferon-gamma inducible protein 16 (IFI16) which is known to mediate inflammasome assembly and initiate pyroptosis, an inflammatory cell death that occurs upon infection." (PMID 40354393, 2025).
infection (continued). "IFI27, IFI6, and IFI16 expansion were predicted to initiate a median of 0.27, 0.72 and 0.52 days post-infection, respectively." (PMID 39575237, 2024). "None of the models in the 95% confidence set included the role of infection clearance or dampening of viral production by IFI16." (PMID 39575237, 2024). "Early in infection, we observed that both 6A and 6D mutants of IFI16 retain their co-localization with ICP4 at the nuclear periphery." (PMID 37283074, 2023). "During early stages of infection, our group and others have observed that IFI16 rapidly moves to the incoming viral DNA at the nuclear periphery, followed by a highly dynamic on/off process of puncta formation." (PMID 37283074, 2023). "This PRM assay was then applied following enrichment of IFI16 via immunoaffinity purification (IPs) at one- and six-hours post infection (hpi) with ICP0-RF HSV-1." (PMID 37283074, 2023). "Our results show a possible relationship between the IFI16 inflammasome and IL-1β secretion during infection with this strain; nevertheless, it is important to elucidate the participation of this inflammasome during ncp-BVDV replication." (PMID 37515181, 2023). "A key characteristic of IFI16 oligomerization is its temporally distinct structural states during infection." (PMID 37283074, 2023). "This increase became more dramatic as infection proceeded, as evidenced by the increases at 3 and 6 hpi in the coverage tracks representing the differences and ratios between IFI16-KO and Ctrl cells." (PMID 35575489, 2022). "For this purpose, we measured glucose concentrations in supernatants from WT and IFI16 KO HFFs (mock or HCMV infected) following infection kinetics from 24 to 144 hpi, using multiplicities of infection (MOI) of 1 and 3 (respectively)." (PMID 35420480, 2022). "Viral genomes colocalized with IFI16 as early as 1 h post-infection and activation of caspase-1 was later detected (4 hpi)." (PMID 35458396, 2022). "HCMV (laboratory strain AD169) infection of WT HFFs triggered lower levels of GLUT4 mRNA expression compared to those observed in IFI16 KO cells at 24 and 48 h postinfection (hpi)." (PMID 35420480, 2022). "To investigate how dsDNA structure governs interactions with IFI16 during infection, we sought to identify patterns in vDNA chromatinization at early times postinfection with ICP0-RF HSV-1 in control fibroblasts." (PMID 35575489, 2022). "Overall, the rate at which viral protein abundances increased during infection was higher in IFI16-KO cells, indicating that IFI16 begins to globally restrict HSV-1 protein expression at or before 3 hpi." (PMID 35575489, 2022). "In both Ctrl and IFI16-KO cells, we observed an accumulation of viral proteins as infection progressed, in agreement with an adequate progression of infection." (PMID 35575489, 2022). "The interplay between cGAS and IFI16 has been explored, revealing cooperation between IFI16 and cGAS upon infection (left)." (PMID 33981307, 2021). "At late stages of infection, pp65 additionally modulates IFI16 function as it induces a re-localization into the cytoplasm thereby antagonizing the antiviral activity of IFI16 inside the nucleus." (PMID 33530304, 2021). "IFI16 deficiency inhibited IRF3 activation- and NF-κB-dependent gene production induced by transfected DNA, and during infection with either MVA or HSV-1." (PMID 34356829, 2021). "These in vivo observations supported the notion that HSV targets IFI16 for degradation during productive infection." (PMID 34552595, 2021). "Increased CASP1 and IFI16 gene expression is compatible with a role for pyroptosis, following the sensing of infection." (PMID 34753817, 2021). "IFI16 is a predominantly nuclear protein that has been described as involved in the induction of innate immune responses upon infection by viruses, including Herpes simplex virus, Epstein-Barr virus, and Kaposi’s sarcoma-associated Herpes virus." (PMID 33981307, 2021).
infection (continued). "In a HBV covalently closed circular DNA (cccDNA) model of infection, overexpression of IFI16 has been shown to increase IFN-β and ISG expression along with decreased euchromatin and increased heterochromatin markers on cccDNA." (PMID 33042875, 2020). "HSV-1 rapidly blocks IFI16-mediated immune responses during infection by catalyzing its degradation, in part via the contribution of ICP0." (PMID 32430029, 2020). "IFI16 has been reported to interact with ASC in response to HSV-1 infection and Kaposi's sarcoma-associated herpesvirus (KSHV) in HFF cells early during infection, and the HSV-1 immediate early protein ICPO is known to downregulate IFI16." (PMID 32101570, 2020). "We expect that these residues mediate both IFI16 punctum formation at the nuclear periphery early in infection and the later filamentation at viral replication compartments." (PMID 31337724, 2019). "To determine if the time-dependent changes in IFI16 filament formation reflect events that occur during a natural multicell infectious process, we studied IFI16 filament formation in cells surrounding a plaque after infection with a low MOI." (PMID 30670617, 2019). "To investigate IFI16's ability to recruit these H3K9MTases onto the incoming KSHV genome during de novo infection, we performed EdU-genome pulldown assay after siRNA-mediated KD of IFI16 in TIME cells." (PMID 31682228, 2019). "To determine the frequency of the IFI16 filaments, we measured IFI16 filament formation under a variety of experimental conditions, including cell density, stage of infection, and multiplicity of infection (MOI)." (PMID 30670617, 2019). "We find that HCMV downregulates IFI16 within the first 24 h of infection of myeloid cells in a US28-dependent manner, but this effect is lost in differentiated dendritic cells." (PMID 31796538, 2019). "In particular, IFI16 is capable of activating the MIEP and driving IE gene expression within the first 6 h of lytic infection of fibroblasts, though at later times IFI16 blocks early and late gene expression." (PMID 31796538, 2019). "IFI16 activates the MIEP during lytic infection, though in these cases an additional viral gene product, UL83, is thought to be required." (PMID 31796538, 2019). "Our results clearly characterized a rapid downregulation of IFI16 during the establishment of latency in monocytes, which occurred within the first 24 h of infection and was also maintained during long-term latency in monocytes and CD34+ HPCs." (PMID 31796538, 2019). "Saturation of this pre-existing intrinsic host defence during HSV-1 ICP0-null mutant infection led to the stable recruitment of PML and IFI16 into vDNA complexes associated with ICP4, and led to the induction of ISG expression." (PMID 29309427, 2018). "During HIV abortive infection, the engagement of the interferon-gamma-inducible-protein 16 (IFI16) in response to cytosolic viral DNA leads to inflammasome assembly and caspase-1 mediated CD4 T cells pyroptosis in lymphoid tissues." (PMID 30459758, 2018). "Few more issues concerning the nuclear/cytosolic interaction of STING and IFI16 and activation of inflammasome remain unanswered, mainly related to the different cellular and infection models analyzed so far." (PMID 29892303, 2018). "Infection with L. monocytogenes should trigger a response similar to that by viral DNA, also inducing IFI16, through DNA fragments or dinucleotides released." (PMID 30540779, 2018). "Correspondingly, qRT-PCR demonstrated that the induction of ISGs (Mx1, ISG15, ISG54) was significantly impaired in both IFI16 or PML depleted cells in response to HSV-1 ICP0-null mutant infection at 9 hpi." (PMID 29309427, 2018). "Saturation of this host defence during HSV-1 ICP0-null mutant infection led to the stable recruitment of PML and IFI16 into vDNA complexes associated with ICP4, and the subsequent induction of ISGs." (PMID 29309427, 2018).
infection (continued). "Nevertheless, IFI16 has been reported to induce ASC-dependent inflammasome activation during infection with some nuclear DNA viruses." (PMID 29892303, 2018). "IFI16-depleted primary keratinocytes were unable to induce IFN-β or IL-6 mRNA following infection with HSV-1." (PMID 28194029, 2017). "Our present results reiterate the necessity of cGAS and IFI16 to drive interferon responses in the human macrophage-like cell line THP-1 during infection with HIV, HSV-1 and CMV or by stimulation with synthetic DNA." (PMID 28186168, 2017). "Despite the significant decrease in IFI16 protein levels by 96 h post induction, a steady increase in IFI16 mRNA occurred, perhaps as a result of IFI16 activation in response to reactive oxygen species generated by EBV productive infection." (PMID 29132393, 2017). "To date, IFI16 degradation has only been reported to occur in HSV-1 de novo infection and lytic reactivation of KSHV-infected cells." (PMID 29132393, 2017). "Nevertheless, collectively our results suggested that H2B is critical in KSHV and HSV-1 genome recognition by IFI16 during de novo infection." (PMID 27764250, 2016). "A recent study with HCMV (Ad169) infection for 6 h in IFI16 knockout (KO) human fibroblast cells suggests that IFI16 is not necessary for the IFN-β response." (PMID 27764250, 2016). "In this study, we observed the rapid formation of IFI16 subnuclear puncta located exclusively at the nuclear periphery upon infection with herpesviruses HSV-1 and HCMV." (PMID 27935834, 2016). "In the study, it was also shown that nuclear translocation of NF-κB and IRF3 upon HSV-1 infection is inhibited by knockdown of IFI16, indicating that this sensor protein can target viral DNA genomes in the infection context." (PMID 27782081, 2016). "In the second phase of infection, however, IFI16 is recruited into puncta which are greater in number than in the first phase and distributed throughout the nucleus." (PMID 27935834, 2016). "Here, we decipher the distinct functions of two viral DNA sensors, IFI16 and cGAS, during active immune signaling upon infection with two herpesviruses, herpes simplex virus 1 (HSV-1) and human cytomegalovirus (HCMV)." (PMID 27935834, 2016). "HMVEC-d cells transfected with siC and siBRCA1 followed by infection with EdU-labeled KSHV were subjected to PLA reaction using anti-IFI16 (mouse) and anti-H2B (rabbit) antibodies." (PMID 27764250, 2016). "PLA analysis revealed that BRCA1 knockdown abolished the acetylation of IFI16 during KSHV de novo infection." (PMID 27764250, 2016). "IFI16 maintained its redistribution into nuclear peripheral foci early in infection; however, these foci grew in both number and size as infection progressed." (PMID 27935834, 2016). "Silencing of H2B, cGAS and STING inhibited IFN-β induction but not IL-1β secretion, and cGAMP activity is significantly reduced by H2B and IFI16 knockdown during infection." (PMID 27764250, 2016). "Further, IECs significantly increased expression of two nucleic acid sensing PRRs, TLR3 and IFI16, following infection with C. concisus BAA-1457, which is suggestive of bacterial lysis within the host cell." (PMID 27677841, 2016). "After several additional hours of infection, IFI16-eGFP appeared eliminated from nucleoli and redistributed into puncta dispersed throughout the nucleoplasm." (PMID 27935834, 2016). "This dynamic behavior was maintained during infection with the transcription- and replication-deficient d109 HSV-1 mutant, suggesting that only the viral nucleocapsid and genome are required to trigger IFI16 peripheral focus formation." (PMID 27935834, 2016). "To further explore this, we monitored IFI16 localization upon infection with several recombinant HSV-1 strains." (PMID 27935834, 2016). "Live-cell imaging, optogenetics, and proteomics were used to define IFI16 functions in space and time following infections with HSV-1 and human cytomegalovirus (HCMV)." (PMID 27935834, 2016).
infection (continued). "Compared to untreated infected cells, C-646 treatment completely abolished the infection induced IFI16 acetylation (lanes 1–6)." (PMID 26134128, 2015). "Recent studies from several laboratories, including ours, have established the PYHIN proteins AIM2 and IFI16 as sensors of viral dsDNA, important for eliciting immune and inflammatory responses to infection." (PMID 25665578, 2015). "A similar to primary infection, we observed increased interaction of IFI16 with ASC in the latently infected BCBL-1 cells which was greatly reduced in C-646 treated cells (lanes 3 and 4)." (PMID 26134128, 2015). "In contrast, during in vitro infection of permissive cells, viral DNA from the capsid enters the IFI16 rich nucleus resulting in the consequences presented by our studies." (PMID 26134128, 2015). "Increased nuclear p300 activation during infection further supports that acetylation of IFI16 is probably mediated by increased p300 activity in the nucleus and not in the cytoplasm." (PMID 26134128, 2015). "Though IFI16 is a predominately nuclear protein, after recognizing KSHV and HSV-1 DNA during de novo infection, the IFI16-ASC complex initially colocalized in the infected cell nucleus and subsequently localized in the perinuclear areas." (PMID 26134128, 2015). "This PYHIN-mediated transcriptional regulation would seemingly function against viruses twofold, as IFI16 was also previously shown to silence viral gene expression by restricting transcription from viral promoters during infection." (PMID 25665578, 2015). "Depletion of IFI16 resulted in a significant 5- or 6-fold increase in viral yield, after infection at an moi of 0.1 or 1.0 pfu/cell, respectively." (PMID 25375629, 2014). "Similar to the results observed in U2OS cells, though expression of each HSV-1 gene increased over the course of infection, viral gene expression was relatively diminished in IFI16-expressing MCF-7 cells over the course of 8 h of infection." (PMID 25375629, 2014). "Several antiviral activities have now been described for IFI16 to counter infection by a broad range of viruses, including α- and γ-herpesviruses, HIV, and Vaccinia virus." (PMID 25375629, 2014). "Further studies are required to fully understand the involvement of IFI16 in chromatin remodeling complexes in the basal state or during infection with HSV-1 or other pathogens." (PMID 25375629, 2014). "Surprisingly, recent studies have extended the range of host immuno-surveillance to the nucleus, where the DNA sensor IFI16 selectively detects the double-stranded DNA genome of herpesviruses during infection." (PMID 23807710, 2013). "Our data showed a two- to three-fold increased induction of CXCL10 in response to HSV-1-infection when macrophages were subjected to IFI16 knock-down." (PMID 23062757, 2012). "In addition, this study also reported that IFI16 is targeted to PML-NBs following infection with an ICP0 mutant HSV-1." (PMID 38399958, 2024). "Importantly, CDK2 knockdown reduced IFI16 filament formation at later stages of infection (8 hpi) and dampened the induction of cytokines in an IFI16-dependent manner." (PMID 37283074, 2023). "For example, although it was fist found that AIM2 is the only ALR that assembles into an inflammasome with ASC in response to cytosolic dsDNA, other studies found that IFI16 forms an inflammasome with ASC upon infection by certain viruses both in the nucleus and the cytosol (e.g. HIV and KSHV)." (PMID 36864667, 2023). "Additionally, using biochemical enrichment, bioinformatics, and mass spectrometry, we identified CDK2 and GSK3β as kinases present at the nuclear periphery during infection and contributing to the IFI16 IDR phosphorylation." (PMID 37283074, 2023). "Although studies have shown that DUBs regulate antiviral immune response through targeting the TLR, RLR, and cGAS-STING signaling cascades, whether DUBs control IFI16 levels to mediate immune response against infection remains unknown." (PMID 37410794, 2023).